MMP2 (matrix metallopeptidase 2)
Diseases named in the same sentence as MMP2 in open-access papers (continued):
Sharing a sentence is not in itself a finding about the gene and the disease.
melanoma (continued). "Through in vitro studies, melanoma cell lines were found to migrate across the BBB under the influence of MMP expression, particularly MMP2 and MMP9, directly affecting BBB permeability and resulting in extravasation." (PMID 37190188, 2023). "Apigenin inhibited melanoma cell migration and invasion by downregulating STAT3 target genes (TWIST1, MMP-2, MMP-9, and VEGF)." (PMID 36829966, 2023). "The downregulation of STAT3-targeted genes MCL-1, MMP-2, MMP-9, and VEGF, which promote cell growth, migration, and invasion, have been identified in melanoma cells after quercetin treatment." (PMID 36829966, 2023). "In conclusion, PCDH9, which is regulated by the circ 0084043-miR-134-5p axis, can suppress malignant biological behavior in melanoma and influence the expression levels of Pyk2, RAC1, Cyclin D1, MMP2, and MMP9." (PMID 36387162, 2022). "JWA inhibits the metastasis of melanoma and gastric cancer cells by inhibiting the expression of the transcription factor SP1 and intergrin αvβ3 through suppressing the ILK and MMP2 signaling pathways." (PMID 36230577, 2022). "In melanoma cells, decline in ARSB increased expression of MMP-9 and pro-MMP2 due to inhibition of SHP2 and activation of phospho-ERK1/2." (PMID 36361933, 2022). "Oroxylin A is reported to be one of the flavonoids that possesses the ability to suppress MMP-2 and -9 activity, hence abolishing B16F10 melanoma lung metastasis." (PMID 35458783, 2022). "The positive effects of Wnt5a on melanoma metastasis also include Ca2+-dependent exosome release, containing the pro-angiogenic and immunosuppressive factors (VEGF, IL-6, and MMP-2), which suppresses endothelial cell branching." (PMID 35162934, 2022). "The expression of MMP2 is a prognostic marker for patients with MM that could independently predict patient survival, and its expression has been related to the poorer survival of patients with melanoma, consistent with varied PCDH9 expression in melanoma cells." (PMID 36387162, 2022). "Melanoma and lymphoma cells in TIMP-3-/- mice had a higher metastatic ability, MMP-2 and MMP-9 expression levels." (PMID 36555545, 2022). "Among theothers, increased activation of ERK1/2 and MMP2, as well as upregulation of MMP14,have been reported in melanoma cells." (PMID 36046354, 2022). "In melanoma cases, it has been reported that apigenin activates the cleaved caspase-3 and PARP expression sites; downregulates Twist1, MMP-2/9, VEGF, p-mTOR, ERK1/2 proteins, and p-AKT; and deactivate FAK/ERK1/2 pathways." (PMID 35965686, 2022). "Our study agreed with the previous investigations that MMP2 and MMP9 can represent a biomarker of malignant melanoma, and downregulating MMP2 expression would increase prognostic survival." (PMID 36452505, 2022). "Several matrix metalloproteinases are expressed in melanoma, the tumor, and the peritumoral stroma, including MMP-1, MMP-2, MMP-9, MMP-13, and MMP-14." (PMID 35558554, 2022). "For example, one study showed that in murine melanoma cells, the interaction of DDR2 with collagen I resulted in increased expression of MMP2 and MMP9 via the intracellular ERK/NF-κB signaling pathway and promoted melanoma cell invasion." (PMID 36119516, 2022). "Other mechanisms involved the inhibition of cancer stem cells in one colorectal liver-metastatic model and suppression of MMPs (MMP2 and MMP9) in two lung metastatic models from SKOV-3 ovarian cancer and B16 melanoma." (PMID 36012338, 2022). "The selective MMP inhibitor ND-322 in a melanoma orthotopic mouse model can inhibit tumor growth and metastatic processes by targeting MMP-2 and MT1-MMP, providing a new avenue for adjuvant treatment options for aggressive melanoma." (PMID 36700222, 2022). "For example, ADAM9 promotes the invasion and metastasis of cancer cells in melanoma by activating MMP1 and MMP2, while ADAM17 can activate MMP2 to treat the disease (prostate cancer and lung injury) by promoting angiogenesis." (PMID 36172139, 2022).
melanoma (continued). "Increased expression of pro-MMP2 and MMP-9 occurred in melanoma cell lines following ARSB silencing, and these increases were associated with increased invasiveness." (PMID 36361933, 2022). "In melanoma tumor cells, activation of PI3K enhanced VM formation by affecting MMP-2 and MT1-MMP activity." (PMID 35321317, 2022). "MT1-MMP promotes melanoma metastasis not only by ECM degradation, but also via regulation of genes involved in tumor cell progress and motility through the activation of MMP2/RAC1 signaling axis." (PMID 33809973, 2021). "ADAM-9 also induces cell signalling leading to increased secretion of the proteolytic enzymes MMP-1 and MMP-2 in fibroblasts and MMP-2 in melanoma cells." (PMID 34067929, 2021). "According to our data, the protein levels of β-catenin and its downstream factors cyclin D1, c-Myc, MMP2, and MMP7 were all markedly decreased in melanoma cells after DHC treatment." (PMID 33833997, 2021). "DHA reduces the migration/invasion of melanoma by down-regulating several matrix metalloproteinases, such as MMP-2 and MMP-13, which are involved in melanoma invasion." (PMID 34069297, 2021). "The ability of the melanoma cells to undergo EMT and develop a more invasive phenotype can also occur through the upregulation and expression of matrix metalloproteinase 2 (MMP2)." (PMID 34439879, 2021). "The anti-proliferative potential of Bai was also studied in melanoma cell lines (A375 and SK-MEL-28), where MMP-2 expression was significantly reduced in cells treated with Bai." (PMID 33498927, 2021). "In another study, crocin (250 and 500 μg/kg) attenuated VEGF, MMP-2, and MMP-9 expressions and TNF-α and IL-6 levels while it elevated IL-10 level in melanoma metastatic model in C57BL/6 mice." (PMID 34956439, 2021). "We provide evidence that mEHT promotes the expression of MMP-2 and ECM degradation of the A2058 melanoma in vivo facilitating the NK cell invasion of the tumor." (PMID 33732640, 2021). "Clinical studies showed significantly increased expression of MMP2 and MMP7 in melanomas, while patients with strong MMP2 or MMP7 had a bad survival." (PMID 33833997, 2021). "For example, the MMP-2 activator, MT1-MMP, has a higher expression in early melanoma than in nevi; moreover, it continues to increase with disease progression, indicating poor patient outcomes." (PMID 35003391, 2021). "Melanoma cells treated with this compound displayed reduced expression of VEGF, its receptor, MMP2/9, and markers of EMT, as well as decreased rates of invasive abilities and angiogenic activity." (PMID 33918883, 2021). "LNMAT knockdown results in decreased matrix metalloproteinases MMP2 and MMP9 expression and inhibits invasion and migration of melanoma cells." (PMID 34638331, 2021). "The microarray gene chip analysis revealed a significant increase of ECM component in aggressive melanoma cells, including the MMP-1, MMP-2, MMP-9, MT1-MMP, and Laminin5." (PMID 33946480, 2021). "RA has also been reported to modulate MMP-2 and MMP-9 expression in vitro in a few cell lines, including T98G GBM cells, THP1 cells, and A375 melanoma cells." (PMID 34572134, 2021). "The inhibition or blockade of soluble molecules responsible for promoting metastasis in melanoma, including MMP1, MMP2, and MMP13 is another approach." (PMID 34207884, 2021). "Results showed that in the murine melanoma B16F10 cell line, API (150 mg/kg) presented antimetastatic activity by suppressing STAT3 phosphorylation and downregulating MMP-2, MMP-9, and VEGF pathways." (PMID 34239802, 2021). "Studies on melanoma have also confirmed that CAFs promote the metastasis and drug resistance of melanoma cells by increasing the expression of MMP1 and MMP2." (PMID 33722297, 2021). "Curcumol upregulated the expression of E-cadherin and downregulated the expression of N-cadherin, MMP2 and MMP9 in mouse melanoma B16 cell." (PMID 32194780, 2020).
melanoma (continued). "In melanoma cells, the STAT3 signaling pathway can promote MMP2 expression, while inhibition of phosphorylated STAT3 expression can significantly inhibit MMP2 expression in vivo, which inhibits tumor cell growth and invasion." (PMID 33330321, 2020). "To determine the downregulation of PD-L1 expression under SB-3CT treatment through the MMP2/9 inhibition, we knocked down (KD) MMP2 or MMP9 with two shRNAs in SK-MEL-28 and A375 melanoma cell lines, respectively." (PMID 32988398, 2020). "Activities of two metalloproteinases: MMP-2 and MMP-9 were studied in the primary (WM793, WM115) and metastatic (Lu1205, WM266-4) melanoma cell lines after 24-h and 48-h treatment with protein kinase inhibitors and their combinations." (PMID 31586300, 2020). "When melanoma cells transfected with CLDN-1, it increased the secretions of matrix metalloproteinase- 2 (MMP-2) reflecting its contribution to the cell invasion process." (PMID 31952355, 2020). "We assessed the therapeutic efficacy of the MMP2/9 inhibitor SB-3CT in combination with the anti-CTLA-4 antibody in two tumor models, B16F10 melanoma and LLC." (PMID 32988398, 2020). "The decrease in MMP2 and MMP9 following curcumol-treated mouse melanoma B16 cells was markedly attenuated by the miR-152-3p inhibitor." (PMID 32194780, 2020). "Genistein was reported to downregulate the expression levels of matrix metalloproteinase-2 (MMP-2) in glioblastoma, melanoma, breast, and prostate cancer cell lines." (PMID 33202681, 2020). "ATX down-regulated MMP-1, MMP-2, and MMP-9, resulting in the inhibition of migration and invasion of melanoma cells in a dose-dependent manner from 5 – 125 μg/ml for 24 h." (PMID 32711429, 2020). "It was demonstrated that melanoma MMP-9 and MMP-2 play a fundamental role in the degradation of the ECM, thus, favoring melanoma spreading towards the surrounding tissues until the formation of distant metastases." (PMID 32392801, 2020). "Our data showed that shikonin inhibited the expression levels of antiapoptotic proteins Bcl-2 and Mcl-1, and enzymatic activities of collagenases MMP-2 and MMP-9, which play vital roles in melanoma metastasis." (PMID 32536866, 2020). "The degradation of ECM by MMPs mainly MMP‐2 and MMP‐9 have been consistently correlated with migration, invasion, and adhesion as well as angiogenesis in many types of cancer including melanoma (Akhavan, Karimi, Ghodrati, & Falahtpishe, 2011)." (PMID 30653763, 2019). "Overexpression of matrix metalloproteinases, especially MMP2 and MMP9 appear to be particularly important in melanoma invasiveness." (PMID 31623313, 2019). "In melanoma cell line (A374), knockdown of MYOF suppressed vasculogenic mimicry via reducing matrix metalloproteinase -2 (MMP-2) and increasing mesenchymal-epithelial transition." (PMID 31477752, 2019). "In melanoma cells, HIF1 and HIF2 induce SRC and FAK signaling to promote invadopodium formation and MMP2-9-dependent matrix degradation." (PMID 31052560, 2019). "STAT3 upregulates nodal factors of angiogenesis, mainly vascular endothelial growth factor (VEGF), hypoxia-inducible factor 1a (HIF-1α) and matrix metalloproteinase-2 (MMP-2) and fosters brain metastasis in melanoma." (PMID 31569642, 2019). "A study reported that highly aggressive melanoma cells can alter their ECM to form VM tubular networks and that the cooperative interaction of Matrix metalloproteinase-2 (MMP-2) -14 or Ln5γ2 chains is required for VM formation." (PMID 31772665, 2019). "Melanoma cells express a number of various types of MMPs such as MMP-1, MMP-2, and MT1-MMP which have essential parts in melanoma vasculogenic mimicry formation and MMP-13 which promotes invasion and metastasis." (PMID 30800067, 2019). "Upregulation of matrix metalloproteinases (MMPs), especially MMP2 and MMP9, appears to be particularly important in melanoma invasiveness." (PMID 31623313, 2019).
melanoma (continued). "In melanoma, the metastatic potential of CXCL8 depends on its ability to promote vascularization, activate MMP2, and enhance anoikis resistance." (PMID 31304688, 2019). "In particular, MMP‐2 and MMP‐9 are well‐known to induce cancer progression and the metastasis of melanoma through the degradation of Type IV collagen, which is the major component of the basement membrane." (PMID 31486124, 2019). "A similar modulatory effect on MMP-2 and VEGF expression has been recently reported for OC in melanoma cells, via the suppression of STAT3 transcriptional pathway." (PMID 31766503, 2019). "Oral administration of daphnane diterpenes-rich Thymelaea hirsuta extract (TH) suppressed MMP2 and MMP9 expression, decreasing lung tumor in mice injected with B16 murine melanoma cells." (PMID 30157785, 2018). "Beforehand α-solanine has been shown to inhibit metastasis, migration and invasion in human melanoma cells (A2058) by inhibiting JNK, PI3K, Akt phosphorylation and NF-κB activation and by decreasing MMP-2/9 activity/expression." (PMID 29799481, 2018). "In mouse melanoma B16F10 cells, casticin treatment also showed that it impaired cell migration and invasion, decreased the expressions of MMP-9, MMP-2, and MMP-1, and inhibited the phosphatidylinositol 3-kinase (PI3K)/Akt and NF-κB signaling pathways." (PMID 30401729, 2018). "In conclusion, MYOF plays an important role in VM and knockdown of MYOF suppresses VM formation via decreasing MMP‐2 and inducing MET in A375 melanoma cells." (PMID 29164766, 2018). "Previously it was proved that silymarin decreased the expression of MMP-2 and MMP-9 in human melanoma cells, having beyond the protective action of hepatocytes an anticancer potential." (PMID 30150935, 2018). "As an example of SFM-DR by CAFs, studies of the drug resistance of melanoma to chemotherapeutic agents have shown that CAFs assisted in metastasis and drug resistance by increasing the expression of IL-6, IL-8, MMP1, MMP2, and MMP972,73." (PMID 29403007, 2018). "Previous investigations have shown significant correlations of TIMPs and uPA with the physiological activities of MMP-2 and MMP-9 and their involvement in the invasiveness, metastasis, and prognosis of melanoma." (PMID 30042328, 2018). "The loss of SOCS1 expression leads to the activation of the JAK2/STAT3 signaling pathway and overexpression of MMP-2, FGF2, and VEGF and enhanced invasion and angiogenesis of melanoma cells, consequently promoting brain metastasis." (PMID 30285793, 2018). "MMP-2 and MMP-9 are especially relevant in melanoma progression, since they play an important role in tumor development, growth, angiogenesis, and metastasis." (PMID 30147443, 2018). "The pathological investigation showed that melanoma tissues overexpressing RICTOR are prone to form VM channels, and this formation was accompanied by AKT membrane translocation and an increase in MMP-2/9 secretion." (PMID 29455662, 2018). "Mosaic vessel and VM channel formation in a B16F10 mouse melanoma model are reduced by thalidomide which inhibits expression of VEGF, NFκB, PCNA, MMP-2 and MMP-9." (PMID 29112161, 2017). "In melanoma, both MMP-14 and MMP-2 degrade laminin-5γ2-chain into promigratory γ2′ and γ2x fragments, which then stimulate invasion and VM formation." (PMID 27034014, 2017). "MMP1, MMP2 and MMP3 are known to be essential proteases for both the growth and metastatic spread of melanoma tumors." (PMID 28146421, 2017). "We also noted that the absence of Mcpt4/Mcpt6/CPA3 was associated with alterations in the expression a range of other genes of potential impact on the melanoma colonization processes: HGF, MMP2, FGF, CXCL2." (PMID 28212574, 2017). "STAT3 activation also promotes melanoma metastasis via increasing the expressions of vascular endothelial growth factor (VEGF), MMP-2 and MMP-914, 32–34." (PMID 28596565, 2017).
melanoma (continued). "RT-PCR documented mRNA expression in all the melanoma cell lines analyzed (WM115, WM266.4, and the positive controls M10 and M14) for VEGF, FGF2, CDH2, CDH5, MMP-2, MMP-9, and the two isoforms of MCAM/MUC18." (PMID 28107182, 2017). "This process is also promoted by the proteolytic activity of matrix metalloproteinase MMP-2, which degrades collagen IV, a major constituent of ECM, and favors melanoma cells to cross the basal lamina and migrate to their secondary sites of growth." (PMID 28107182, 2017). "High microenvironmental pressures increased MMP-2 and MMP-9 expression in melanoma cells, induced ECM remodeling and VM channel formation and accelerated tumor cell invasion." (PMID 27034014, 2017). "Our further analysis showed that KMT2A knockdown suppressed the expression of MMP2, MMP9 and promoted the cleavage of Caspase3/Caspase7/Caspase9 and PARP in melanoma cells, and repressed the expression of hTERT and the Nanog/oct-4/sox-2 stem cell markers." (PMID 28726783, 2017). "MMP‐14 and its downstream effector MMP‐2 are major players in angiogenesis and tumorigenesis, and MMP‐13 promoted tumor angiogenesis, melanoma invasion, and metastasis." (PMID 27932444, 2017). "We retrospectively analyzed melanoma tumors for LKB1 and MMP-2 using immunohistochemistry from 90 melanoma patients, including 27 BRAF V600E patients and 63 BRAF wild type patients, and correlated LKB1 expression with tumor clinicopathological parameters." (PMID 29371951, 2017). "The pathological investigation showed that melanoma tissues overexpressing Rictor are prone to form VM channels, and this formation is accompanied by AKT membrane translocation and an increase in MMP‐2/9 secretion." (PMID 28699701, 2017). "It was found that treatment of honokiol, NAC and DPI reduced the expression of MMP-2 and MMP-9 in Hs294t and SK-Mel28 melanoma cells, thus suggesting a common mechanism of action by these agents." (PMID 26760964, 2016). "Expression of MMP-2 and MMP-9 has also been shown to promote cell invasion and metastasis of melanoma." (PMID 26517521, 2016). "Melanoma cells derived from Wnt, acting through Fz receptors, induce MMP-9 and MMP-2 expression, which plays a vital role in cell migration and invasion." (PMID 26968952, 2016). "MMPs, specifically MMP-2 and MMP-9, are well characterized for their key roles in tumor progression, cell migration and invasion of cancers including melanoma." (PMID 26760964, 2016). "And lastly, we found that MALAT1 promoted melanoma cell growth and metastasis by competitively binding the miR-22, up-regulating MMP14 and Snail, and having downstream effects on MMP2 and E-cadherin protein." (PMID 27564100, 2016). "Lgl1 promotes the cell adhesion and inhibites cell migration by downregulating the expression of MMP2 and MMP14, and re-expressing of E-cadherin in melanoma cells." (PMID 26934648, 2016). "The gelatinases, MMP-2 and MMP-9, primarily cleave collagen type IV and are believed to play a crucial role in the progression of melanoma cells." (PMID 27271600, 2016). "Only several publications have concerned the evaluation of the utility of measurements of VEGF, MMP-2, MMP-9, TIMP-1, and YKL-40 in serum in melanoma; what is more, the results are controversial." (PMID 26002577, 2015). "Various types of MMPs affect melanoma metastasis by degrading ECM; MMP-1, MMP-2, and MT1-MMP have essential parts in melanoma VM formation." (PMID 25749207, 2015). "Only few publications concerned the evaluation of the concentrations of MMP-2 and MMP-9 in serum of patients with melanoma." (PMID 26002577, 2015).